AR (androgen receptor)
Diseases named in the same sentence as AR in open-access papers (continued):
Sharing a sentence is not in itself a finding about the gene and the disease.
squamous cell carcinoma (11 papers, 2017 to 2025). A carcinoma arising from squamous epithelial cells. "Moreover, downregulation of AR in PDGFRα+ fibroblasts from squamous cell carcinomas induces the activation of cancer-associated fibroblasts, which remodel the ECM within the tumor microenvironment." (PMID 39292748, 2024). "AR immunostaining was also proposed for the distinction of sebaceous from basal cell and squamous cell carcinoma of the skin." (PMID 38790919, 2024). "More importantly, when the squamous cell carcinoma cultures are exposed to conditioned medium from CAFs pretreated with either RARβ or AR antagonists, the CAF-induced cisplatin resistance is completely abolished." (PMID 30925918, 2019). "Moreover, IHC performed in selected cases (focused on ductal–myoepithelial panel, AR negativity, and low Ki-67 index) allowed for the differential diagnosis with adenoid cystic, epithelial–myoepithelial, or squamous cell carcinomas." (PMID 41440486, 2025).
urothelial carcinoma (11 papers, 2013 to 2025). A malignant neoplasm derived from the transitional epithelium of the urinary tract (urinary bladder, ureter, urethra, or renal pelvis). "However, considering that 27.7% of muscle-invasive urothelial carcinomas were AR positive (5.6% with strong AR staining) in our study, the diagnostic potential of AR appears to be limited in this setting." (PMID 38790919, 2024). "Low AR was linked to advanced tumor stage (pTa versus pT2-4; p < 0.0001) in urothelial carcinoma." (PMID 38790919, 2024). "AR protein expression has been found to decrease in tumors at higher pathological stages and grades, indicating that the loss of AR expression is associated with higher grade urothelial carcinomas (UCs) and invasive UCs, but has limited effect on the prognosis for survival." (PMID 23599788, 2013). "Overall, these data underscore the therapeutic relevance of the androgen receptor as a potential target in urothelial carcinoma, particularly in the era of personalized treatment strategies." (PMID 41463239, 2025). "Technical issues: Of our 2710 urothelial carcinomas, 2398 (88.5%) were interpretable for AR protein expression analysis." (PMID 41463239, 2025). "Further data from several preclinical and clinical studies have also supported the antitumor efficacy of androgen deprivation therapy on AR-expressing urothelial carcinomas." (PMID 41463239, 2025). "Among 1726 pT2–pT4 urothelial carcinomas, the distribution of AR immunostaining intensity differed significantly across pT stages (p = 0.0014) and according to nodal status (p = 0.0060) as well as venous invasion (p = 0.0095)." (PMID 41463239, 2025). "Nuclear AR positivity was observed in 22.9% of 2398 urothelial carcinomas, including 399 (16.6%) with weak, 108 (4.5%) with moderate, and 41 (1.7%) with strong staining." (PMID 41463239, 2025). "The correlation between high AR expression and the non-invasive stage for urothelial carcinoma is consistent with results from several earlier studies." (PMID 38790919, 2024). "In this review, we summarize what is known about androgen receptor signaling in urothelial carcinoma as well as in tumor-infiltrating immune cells, reviewing preclinical and clinical data." (PMID 38398136, 2024). "For example, the reported AR positivity ranges 13–54% in urothelial carcinoma, 54–100% in salivary duct carcinoma, 22–78% in basal cell carcinoma of the skin, and 13–67% in oral squamous cell carcinoma." (PMID 38790919, 2024). "Androgen receptor has been found to be variably expressed in urothelial carcinoma specimens, with AR staining present in 12% to 77% of patients." (PMID 28085048, 2017). "Significant or insignificant down-regulation of AR expression in high-grade or MI urothelial carcinomas, compared with low-grade or NMI tumors, has also been found." (PMID 28362839, 2017). "Another notable finding of our study was the significant association between AR positivity and poor prognosis in muscle-invasive urothelial carcinomas, although this relationship did not remain significant in the multivariate analysis." (PMID 41463239, 2025). "AR in urothelial carcinomas: AR staining was always nuclear." (PMID 41463239, 2025). "Two studies in urothelial carcinomas have suggested a link between high AR expression and unfavorable prognosis, while others could not confirm these findings or even described associations between AR positivity and favorable disease course." (PMID 41463239, 2025). "Preclinical studies evaluating the effect of androgens and AR-signaling on urothelial carcinoma tumorigenesis have found that AR-signaling may promote tumor formation." (PMID 28085048, 2017). "Androgen and the androgen receptor (AR) were previously hypothesized to account for the gender difference in the incidence of urothelial carcinomas; however, the role of AR in the development and progression of UUTUCs is not well understood." (PMID 23599788, 2013).
urothelial carcinoma (continued). "Other enriched genes we found (AR, GNB3, HHLA2 and IL4) were related to transitional cell carcinoma of the bladder (also known as Urothelial carcinoma)." (PMID 35565241, 2022). "The disadvantage of AR is the relative lack of specificity, as other neoplasms including urothelial carcinoma or salivary gland tumors may also be AR positive." (PMID 28555048, 2017). "However, for other forms of urothelial carcinomas, the role of AR in UUTUC development and progression is not clear." (PMID 23599788, 2013). "In both AR-positive and AR-negative cell lines, menin interacts with the transcription factor ERH, which has recently been reported to induce cell migration and invasion in urothelial carcinoma through the activation of c-Myc." (PMID 39336822, 2024).
acute myeloid leukemia (10 papers, 2007 to 2025). Acute myeloid leukemia (AML) is a group of neoplasms arising from precursor cells committed to the myeloid cell-line differentiation. "In the same study, a positive influence of high AR expression on survival in cancers such as acute myeloid leukaemia or cutaneous melanoma was documented, highlighting a dual effect that AR can exhibit depending on the nature of the malignancy." (PMID 35661403, 2022). "In addition, several recently developed EP300/CREBBP bromodomain inhibitors have been reported to mediate antiproliferative responses in hematologic cancer cell lines, such as acute myeloid leukemia (AML) and multiple myeloma cell lines and AR-positive prostate cancer cell lines." (PMID 29884215, 2018).
bladder urothelial cancer (10 papers, 2013 to 2026). "Several earlier studies had also described a progressive loss of AR expression during grade and stage progression of urothelial carcinomas of the urinary bladder." (PMID 41463239, 2025). "Taken together, preclinical studies of AR and urothelial bladder cancer to date have strongly established a causal effect of AR signaling that can be clinically leveraged for therapy." (PMID 38398136, 2024). "The data generated from this study provide the first line of evidence that demonstrates a promotional role of transgenic AR expression in enhancing the susceptibility to BBN-induced bladder urothelial carcinomas in mice." (PMID 26862755, 2016). "In bladder urothelial carcinoma and THCA, the AR/ERα ratio showed modest effects associated with worse survival (HR = 1.12; 95% CI, 1.02–1.23; P = 0.018 and HR = 1.11; 95% CI, 1.01–1.23; P = 0.027, respectively)." (PMID 41486951, 2026). "Androgen receptor signaling is an important target to investigate in urothelial carcinoma of the bladder because basic and clinical evidence strongly suggests that the androgen receptor is involved in bladder carcinogenesis." (PMID 38398136, 2024). "Moreover, conditional expression of transgenic AR in female R26hARLoxP/+:Upk3aGCE/+ mice increased the incidence of BBN-induced bladder urothelial carcinomas compared to female R26hARLoxP/+ control littermates." (PMID 26862755, 2016). "The role of androgen receptor (AR) in urothelial carcinoma of the ureter and renal pelvis remains unclear; however, AR has been demonstrated to affect urothelial carcinoma of the bladder." (PMID 23599788, 2013). "Based on the observed down-regulation of AR in bladder urothelial cancer tissues, it has been suggested that LINC00460 might exert its oncogenic roles through modulation of AR expression." (PMID 34831421, 2021).
cardiac hypertrophy (10 papers, 2011 to 2025). "In summary, AAS abuse directly affects both cardiac and vascular cells through androgen receptor-mediated pathways, initiating a cascade of molecular events that culminate in cardiac hypertrophy and endothelial dysfunction." (PMID 41303522, 2025). "Comparably, anti-androgenic treatment with an AR antagonist Flutamide lead to reduction in cardiac hypertrophy in a rat model of hypertension." (PMID 36817598, 2023). "Epidemiological and experimental studies suggest that AR-specific ligands can induce cardiac hypertrophy." (PMID 37998524, 2023). "To examine the involvement of CaMKII/MEF2 and AR signaling pathways in testosterone-induced cardiac hypertrophy, we measured cellular size and [3H]-leucine incorporation, which are both accepted indicators of cardiac myocyte hypertrophy." (PMID 28955223, 2017). "Testosterone is known to induce cardiac hypertrophy through androgen receptor (AR)-dependent and -independent pathways, but the molecular underpinnings of the androgen action remain poorly understood." (PMID 28955223, 2017). "The influence of androgen receptor signalling in cardiac hypertrophy has been proposed earlier, either by acting directly on the heart or by affecting the vascular system." (PMID 26930585, 2016). "Future research should delve deeper into the mechanisms behind AR's role in cardiac hypertrophy, especially focusing on the functional implications of AR45 and the gender-specific effects of AR." (PMID 37998524, 2023). "Several animal models exist, that highlight the AR-mediated influence of Testosterone and DHT on cardiac hypertrophy." (PMID 36817598, 2023). "Because the AR and the MEF2 pathways of transcriptional regulation both control gene-expression programs related to cell growth—a crucial requisite for the induction of cardiac hypertrophy—we investigated whether these pathways are linked in testosterone-induced cardiac myocyte hypertrophy." (PMID 28955223, 2017). "In mice with angiotensin II induced hypertrophy, knockout of AR leads to a significant reduction in cardiac hypertrophy and fibrosis, and in a rat model of myocardial infarction, low levels of DHT were described to be protective against cardiac hypertrophy." (PMID 36817598, 2023). "Furthermore, AR stimulation increases the expression and number of androgen receptors in the myocardium, and chronic abuse of AAS leads to changes in cardiac phenotype and the induction of ventricular hypertrophy through genomic and non-genomic signaling mechanisms." (PMID 41303522, 2025).
ductal carcinoma (10 papers, 2012 to 2025). "Immunohistochemical: (++), CK7(+++), AR(++), Brg-1(+), Her-2(2+), Ki67(+, approximately 80%), consistent with high-grade ductal carcinoma, considering salivary gland origin." (PMID 39928775, 2025). "Immunohistochemical: EMA(++), CK7(+++), AR(++), Brg-1(+), Her-2(2+), Ki67(+, approximately 80%), consistent with high-grade ductal carcinoma, considering salivary gland origin." (PMID 39928775, 2025). "In AR−/FOXA1-cases, the pathological type is mainly ductal carcinoma associated with more central fibrosis and higher grade of ductal carcinoma In situ." (PMID 39777114, 2024). "AR-negative TNBC was reported in 361 patients of 487 and comprised mainly of ductal carcinoma with higher grade and more lymphocytic infiltration and central fibrosis than AR-positive cases." (PMID 39777114, 2024). "AR expression is also higher in the ductal carcinoma region relative to the SCNEC region." (PMID 37628903, 2023). "In addition, for patients with ductal carcinoma and androgen receptor positivity, adjuvant treatment with complete androgen blockade can be considered." (PMID 35739348, 2022). "Therefore, in patients with ductal carcinoma or NOS metastatic adenocarcinoma with androgen receptor expression ≥ 10%, treatment should include complete androgen blockade." (PMID 35739348, 2022). "AR expression in BC tissue samples has been associated with a better prognosis and the lack of AR expression correlates with transformation from “in situ” to invasive basal subtype ductal breast carcinoma." (PMID 26862856, 2016). "Second, in the group of HR-positive ductal carcinoma, HIF-1α participates in the most important factor 1 along with SATB1 providing factor loadings opposite to those of AR, ER and BCL2, independently of Ki67 expression (factor 3)." (PMID 22424533, 2012).
ductal carcinoma in situ (10 papers, 2005 to 2025). "The high TROP2 expression was associated with higher androgen receptor expression, ductal carcinoma in situ, apocrine histology, lymphovascular invasion, and lymph node involvement." (PMID 40943224, 2025). "Ductal carcinoma in situ(p = 0.003), oestrogen receptor (ER) (p = 0.001) and progesterone receptor (PR) (p = 0.001) positivity and luminal IHC molecular subtype(p = 0.016) were significantly associated with AR-positive status." (PMID 32928183, 2020). "We considered AR and its ratio with other hormone receptors, analyzing also studies including patients with ductal carcinoma in situ and with early and advanced BC, as well." (PMID 36111296, 2022). "Although several studies made an effort to establish the prognostic role of AR in invasive BC, little has been done for ductal carcinoma in situ of the breast (DCIS)." (PMID 36111296, 2022). "AR expression reduces with tumor grade progression in both ductal carcinoma in situ (DCIS) and metastatic carcinoma, yet is expressed at a higher rate than ER at any tumor grade." (PMID 34638264, 2021). "A retrospective analysis of 42 Ductal Carcinoma in situ of the breast (DCIS) patients treated with surgery followed by radiotherapy showed that AR expression was considerably higher in relapsed tumors (p = 0.0005), whereas ERα was higher in non-relapsed ones." (PMID 31952272, 2020). "We previously demonstrated an unfavorable prognostic role of the AR/ER ratio in different subsets of patients (i.e., patients with ductal carcinoma in situ of the breast), independently of treatment (i.e., surgery alone or surgery plus radiotherapy)." (PMID 31110518, 2019). "Similarly, we previously highlighted the unfavorable prognostic role of the AR/ER ratio in patients with in situ ductal carcinoma, independently of treatment." (PMID 36111296, 2022). "AR is also an important prognostic indicator and studies have shown that ductal carcinoma in situ of the breast with negative AR expression has a worse prognosis and a higher recurrence rate." (PMID 38263473, 2024). "In malignancy, grade 1 and 2 ductal carcinoma in situ express ER, PR and AR, whereas the majority of grade 3 ductal carcinoma in situ are ER and PR negative but continue to be AR-positive." (PMID 16457685, 2005).
liver diseases (10 papers, 2019 to 2025). "The androgen receptor (AR) signaling pathway plays a critical role in regulating hepatocyte growth and apoptosis, and its dysfunction may be implicated in the pathogenesis of liver diseases." (PMID 40537476, 2025). "AR signalling also plays an important role in normal liver functioning and the progression of liver diseases." (PMID 40869103, 2025). "It was observed that AR, CREB1, ACVR2A, and CXCL12 were down-regulated in T1DM-associated liver disease; however, they exhibited up-regulation after NAC treatment." (PMID 40001479, 2025). "A subsequent genome-wide association study (GWAS) identified shared single-nucleotide polymorphisms (SNPs) in the genes AR, EDIL3, MACROD2, PCSK5, RUNX1T1, TENM4, and ZEB2 between PN and liver disease from the FinnGen cohort." (PMID 38397136, 2024). "The AR compound has also shown promising clinical efficacy in a wide range of diseases, such as digestive disease, liver disease, knee synovitis, and arteriosclerosis." (PMID 39215362, 2024). "Androgen/androgen receptor (AR) signaling plays important roles in the progression of liver diseases and has been proven to promote the HCC initiation at early-stage but suppress the HCC progression at late-stage." (PMID 32792008, 2020). "While AR knockout mouse models have suggested that AR suppression can reduce fibrosis in certain liver diseases, other studies have reported that AR may promote fibrosis, particularly in specific contexts such as alcohol-induced liver fibrosis." (PMID 40869103, 2025). "Similarly, AR is a ligand-activated transcription factor, which plays a crucial role in normal liver function and the progression of the liver diseases including HCC." (PMID 34603388, 2021). "Furthermore, AR also has good effect for other liver diseases." (PMID 39215362, 2024). "Moreover, Androgen receptor (AR) signaling played important roles in normal liver function and in progression of liver diseases, the downregulation of AR in the hsa_circ_0008774-related ceRNA network indicated that hsa_circ_0008774 may be the upstream regulator of AR signaling." (PMID 34094907, 2021). "Wen-Lung and colleagues studied the role of AR on different liver diseases, but univocal results have not yet been obtained." (PMID 33187340, 2020).